PGRMC1 (progesterone receptor membrane component 1)
Diseases named in the same sentence as PGRMC1 in open-access papers (continued):
Sharing a sentence is not in itself a finding about the gene and the disease.
liver cancer (3 papers, 2019 to 2023). An epithelial or non-epithelial malignant neoplasm that arises from the liver. "Our findings revealed altered expression of several CmPn members (including CCM1/3 and PAQR7/8) between normal and tumor tissues and among different liver cancer subtypes, which was also observed for PGRMC1." (PMID 36980321, 2023). "Researchers have shown that PGRMC1 contributes to doxorubicin-induced chemoresistance in uterine sarcoma and PGRMC1 knockdown increases the sensitivity of colon and liver cancers to erlotinib treatment." (PMID 35152910, 2022). "Recently, researches have demonstrated that PGRMC1 mediates doxorubicin-induced chemoresistance in uterine sarcoma, and PGRMC1 knockdown increases the sensitivity of colon and liver cancers to erlotinib treatment, thus implicating PGRMC1 as a novel and promising target for cancer therapeutics." (PMID 35152910, 2022). "When comparing protein expression of key CmPn players within liver cancer subtypes, PAQR7, PGRMC1, and nPRs proteins were significantly differentially expressed only when comparing HCC to all other subtypes, which was also observed in our preliminary TCGA analysis between HCCs and CCAs." (PMID 36980321, 2023).
Obesity (3 papers, 2018 to 2025). Accumulation of substantial excess body fat. "Moreover, Pgrmc1 KO mice were also more vulnerable to early stage of NASH, showing high levels of alanine aminotransferase, obesity-linked pro-inflammatory cytokines, and fibrosis markers." (PMID 30356113, 2018).
oral cancer (3 papers, 2016 to 2023). "Among all the metastasis‐related candidates, membrane‐associated progesterone receptor component 1 (PGRMC1) was selected for further investigation and show potency as an oral cancer therapeutic targets." (PMID 32672400, 2020). "Using proteomic and RNA interference approaches in oral cancer cell models, Huang and co-workers showed that PGRMC1 induced epithelial-mesenchymal transition (EMT) via SIP1, SNAIL, and Twist in these cells." (PMID 37887342, 2023). "Together, gross specimens and histological examination indicated that the knockdown of PGRMC1 can suppress distant metastasis of oral cancer cells in vivo." (PMID 32672400, 2020). "By using oral cancer cells carrying a shRNA to inactivate the PGRMC1 gene function, we addressed the role of PGRMC1 in the development of tumour metastasis to the lung in vivo." (PMID 32672400, 2020). "Due to the comprehensive effects of PGRMC1 on modulating oral cancer invasion, migration and proliferation, we examined the role of PGRMC1 in oral cancer invasion in vivo." (PMID 32672400, 2020). "We demonstrated that the development and metastasis of the oral cancer OC3 cells in vivo depend substantially on PGRMC1 expression." (PMID 32672400, 2020). "Altogether, these results demonstrated that PGRMC1 was required for human oral cancer invasion and migration via regulating EMT‐inducing transcription factors SIP1, Snai1 and Twist." (PMID 32672400, 2020). "To examine the role of PGRMC1 in oral cancer invasion, we used siRNA to down‐regulate the expression of PGRMC1." (PMID 32672400, 2020). "Our results demonstrated that PGRMC1 is crucial for oral cancer invasion and motility." (PMID 32672400, 2020). "Among these binding partners, plasminogen activator inhibitor RNA‐binding protein 1 (PAIR‐BP1) might be an essential component for PGRMC1‐mediated oral cancer invasion." (PMID 32672400, 2020). "To investigate whether PGRMC1 knockdown interferes oral cancer proliferation ability and how PGRMC1 acts, we performed MTT assay." (PMID 32672400, 2020). "Thus, our results point to p1932 as a modulator of the transduction signal pathway mediated by this protein and, given a well-established involvement of PGRMC1 in tumorigenesis, highlight a possible therapeutic potential of p1932 for the treatment of oral cancer." (PMID 26814504, 2016). "PGRMC1 might modulate protein synthesis through mRNA modification via binding with PAIR‐BP1 or through transcriptional regulation via translocating into nucleus to upgrade the invasion, migration and proliferation abilities of oral cancer." (PMID 32672400, 2020).
polycystic ovary syndrome (3 papers, 2010 to 2022). A disorder that manifests as multiple cysts on the ovaries. "Lower levels of PGRMC1 were also detected in the peripheral leukocytes of women with polycystic ovary syndrome (PCOS), suggesting that decreased PGRMC1 levels in women with PCOS is an indication of altered follicle development and reduced ovulatory capacity." (PMID 35626669, 2022).
alcoholic liver damage (2 papers, 2023 to 2024). "Since low expression of PGRMC1 is vulnerable to alcoholic liver damage, the loss of PGRMC1 expression may increase susceptibility to ALD." (PMID 37070746, 2023). "Previous studies on Pgrmc1 and alcoholic liver disease have suggested that Pgrmc1 KO mice experienced heightened ER stress." (PMID 38397828, 2024).
cardiac failure (2 papers, 2021 to 2023). "In isoproterenol-induced cardiac injury, Pgrmc1 knockout resulted in less fibrosis and low heart failure marker expression." (PMID 36899888, 2023). "This study is clinically important because mitochondrial defects in Pgrmc1 KO mice hearts represent the late phase of cardiac failure." (PMID 33888830, 2021). "Conversely, HFD Pgrmc1 KO hearts induced various heart failure markers." (PMID 33888830, 2021). "Accordingly, HFD Pgrmc1 KO mice were prone to cardiac lipotoxicity, featuring high levels in markers of inflammation, endoplasmic reticulum stress, oxidative stress, fibrosis, and heart failure." (PMID 33888830, 2021). "Furthermore, as a cardiac failure marker, the expression of ANP was increased (p < 0.05, 2.44-fold vs. HFD WT) in the hearts of HFD Pgrmc1 KO mice." (PMID 33888830, 2021).
congenital cataracts (2 papers, 2021 to 2024). "These two patients, in addition to the family with congenital cataracts we studied, provide strong evidence that loss of function variants in PGRMC1 cause X-linked paediatric cataract." (PMID 33867527, 2021). "A truncating deletion of PGRMC1 was found in the etiology of developmental cataracts, rationalized by a potential disruption of PGRMC1’s interaction with CYP51A1 and consequently altered cholesterol biosynthesis." (PMID 38804287, 2024). "Cataract formation following morpholino-induced gene knockdown in zebrafish and an additional report of two other unrelated males with non-syndromic intellectual disability and PGRMC1-disrupting deletions and congenital cataracts support this as a novel gene involved in cataractogenesis." (PMID 33867527, 2021).
dementia (2 papers, 2021 to 2024). Loss of intellectual abilities interfering with an individual's social and occupational functions. "While PGRMC1 has attracted a lot of attention as a therapeutic target for regulating a variety of disease conditions such as dementia and adipogenesis, pharmacological interventions for controlling them remain to be developed." (PMID 34209885, 2021). "Therefore, we aimed to examine whether PGRMC1 activation could be an option for providing an innovative dementia treatment and developing prevention strategies." (PMID 38397828, 2024).
dyslipidemia (2 papers, 2018 to 2024). "In the lipid metabolism, studies reported that the four protein complexes including SREBP, SCAP, INSIG, and PGRMC1 in the endoplasmic reticulum may be the important regulators of dyslipidemia caused by AAPD12,61." (PMID 38760414, 2024). "PGRMC1 is a potential target for treatment of cancer and several other diseases such as metabolic syndrome or neurological disease." (PMID 30087538, 2018).
endometrial adenocarcinoma (2 papers, 2021 to 2022). "In the well-differentiated endometrial adenocarcinoma cell line, Ishikawa cells, miR-98 gain of function repressed PGRMC1 expression and cell proliferation, and PGRMC1 was confirmed to be a direct target of this miRNA." (PMID 35406659, 2022). "Similar studies were conducted using Ishikawa cells, a cell line derived from an endometrial adenocarcinoma, and revealed that transfected miR-98, a Let-7 family member, suppressed PGRMC1 expression through a direct interaction with the 3′-UTR region of PGRMC1." (PMID 34885064, 2021).
Endometrial Cyst (2 papers, 2022 to 2025). It is caused by endometriosis, and formed when a tiny patch of endometrial tissue (the mucous membrane that makes up the inner layer of the uterine wall) bleeds, sloughs off, becomes transplanted, and grows and enlarges inside the ovaries. "The formation of endometrial cysts is a typical phenotype of senescence in mice and humans, suggesting that there is a link between PGRMC1 and senescence in the uterus." (PMID 36008941, 2022). "Conditional deletion of the Progesterone receptor membrane component 1 (Pgrmc1) gene using Amhr2-Cre led to subfertility and the development of endometrial cysts in female mice, revealing its significance in maintaining uterine tissue homeostasis and fertility." (PMID 40149986, 2025). "Interestingly, age-related endometrial cysts in the uterus form earlier in PGRMC1-knockout mice than in normal mice." (PMID 36008941, 2022).
head-neck squamous cell carcinoma (2 papers, 2019 to 2023). "And the over-expression of PGRMC1 was strongly correlated with various metabolic process activity as well as cancer metastasis and cell proliferation features in human head-neck squamous cell carcinoma patient's cohort." (PMID 31970154, 2019). "Our results demonstrated that PGRMC1 expression served as a predictor for worse OS (HR = 1.95, P = 0.0005) in head-neck squamous cell carcinoma." (PMID 31970154, 2019).
hepatic diseases (2 papers, 2018 to 2025). "Moreover, Pgrmc1 KO mice were predisposed to liver inflammation and fibrosis; therefore, loss of Pgrmc1 can increase the risk of hepatic diseases such as NAFLD and NASH under high-fat diets typical of western societies." (PMID 30356113, 2018).
Hepatic steatosis (2 papers, 2018 to 2025). Steatosis is a term used to denote lipid accumulation within hepatocytes. "In our previous study, we demonstrated that Pgrmc1 loss in HFD‐fed mice exacerbated hepatic steatosis and steatohepatitis through enhanced de novo lipogenesis, a liver‐specific metabolic pathway that generates malonyl‐CoA for fatty acid synthesis." (PMID 41208560, 2025). "Thus, we focused on hepatic lipogenesis to investigate the mechanism of increased hepatic steatosis in the loss of Pgrmc1." (PMID 30356113, 2018). "Loss of Pgrmc1 increased mature SREBP-1 protein level, suggesting that induction of hepatic steatosis in Pgrmc1 KO mice might be triggered by de novo lipogenesis." (PMID 30356113, 2018). "Therefore, our data suggest that Pgrmc1 KO mice are genetically more vulnerable to lipotoxicity acquired by hepatic steatosis." (PMID 30356113, 2018).
insulinoma (2 papers, 2021 to 2025). "In parallel to the genetic KD and KO approaches, we used a chemical strategy to disrupt PGRMC1 function in rat insulinoma INS-832/13 pancreatic β-cells, in order to evaluate the fate of mutant proinsulin in a physiologically relevant cell culture system." (PMID 34645803, 2021). "Specifically, the membrane progesterone receptor component PGRMC1 has been reported to cross-talk with and enhance GLP-1-induced insulin secretion in a rat insulinoma cell line." (PMID 40002193, 2025).
lipid metabolic disorders (2 papers, 2021 to 2025). "Thus, it could be reckoned that PGRMC1 plays a dual role in the regulation of glucose-lipid metabolic disorders." (PMID 34970218, 2021). "First, prebiotic B-GOS has been shown to alleviate OLZ-induced lipid metabolism disorders by increasing the abundance of AKK and counteracting OLZ’s negative effects on the PGRMC1 pathway." (PMID 40176900, 2025).
lymph node metastasis (2 papers, 2020 to 2021). "Larger tumor size and lymph node metastasis were found to correlate with overexpression of PGRMC1 and patients observed with mPRα and PGRMC1 expressing tumors have poor disease-free and overall survival." (PMID 32867363, 2020).
Miscarriage (2 papers, 2023 to 2024). A pregnancy that ends at a stage in which the fetus is incapable of surviving on its own, defined as the spontaneous loss of a fetus before the 22th week of pregnancy. "Moreover, the importance of PGRMC1 in mediating P4 signaling is evidenced by the fact that women who suffered from recurrent miscarriages (RM) and PTB have decreased PGRMC1 expression." (PMID 38337402, 2024).
ovarian failure (2 papers, 2022 to 2023). "With regard to patients with chemotherapy-induced primary ovarian insufficiency, it has been shown in experiments with rats that HA appears to have a preventive effect in these patients due to the promotion of granulosa cells and upregulation of PGRMC1 expression." (PMID 35767191, 2022).
ovarian tumor (2 papers, 2015 to 2021). "This is supported by the observation that PGRMC1 localizes to the nucleus in more advanced and rapidly growing ovarian tumors." (PMID 34885064, 2021). "Insight into the involvement of PGRMC1 in regulating efflux pumps/transporters was obtained from xenograft studies in which ovarian tumors were derived from SKOV-3 cells in which PGRMC1 was depleted." (PMID 34885064, 2021). "PGRMC1 has been previously shown to play a key role in ovarian tumor growth, apoptosis resistance, invasion, angiogenesis, drug resistance and metastasis." (PMID 27867772, 2015). "Thus, even though they grow more slowly, PGRMC1-deplete ovarian tumors express several ABC transporters, which likely accounts for their greater resistance to cisplatin." (PMID 34885064, 2021). "Finally, Mifepristone could actually promote ovarian tumor growth via a PGRMC1-dependent mechanism since the PGRMG1 antagonist, AG 205, has been shown to attenuate Mifepristone growth-promoting actions." (PMID 34885064, 2021). "Searching this database (July 2021) revealed that both mRNA and protein levels of PGRMC1 and PGRMC2 are significantly elevated in ovarian tumors." (PMID 34885064, 2021). "In the present study, we have analyzed PGRMC1 levels in over 600 tumor sections, including a larger cohort of lung tumors than in previous studies, and report the first clinical analysis of PGRMC1 levels in human oral cavity and ovarian tumors compared to corresponding nonmalignant tissues." (PMID 27867772, 2015).
prostate carcinoma (2 papers, 2020 to 2021). A carcinoma that arises from epithelial cells of the prostate gland. "Although PGRMC1 was studied in a variety of human cancers, only one report so far showed its involvement in prostate cancer." (PMID 34572596, 2021). "In line with this, PGRMC1 silencing favored an enhanced NFAT1 accumulation in cells treated with P4, thus favoring cell proliferation similar to that in prostate cancer cells." (PMID 33076541, 2020). "In addition, we analyzed the expression levels of PGR, PGRMC1, and PGRMC2 genes in prostate cancers." (PMID 34572596, 2021). "Meanwhile, PGR and PGRMC1 downregulation also had no significant impact on overall survival but a moderate impact on the progression-free interval in prostate cancers." (PMID 34572596, 2021). "In addition, PGRMC1 was reported to distinguish Gleason score 3 versus 4 tumors of prostate cancers, but the clinical significance was not clear." (PMID 34572596, 2021).
renal cell carcinoma (2 papers, 2017 to 2024). "In this report, we made a systematic, integrative biological assessment for PGRMC1 in renal cell carcinoma (RCC) by a quantitative proteomic identification, immunohistochemical detection, and its clinic pathologic significance analysis." (PMID 28107520, 2017). "The combination of PGRMC1 and ATP1A1 protein levels can serve as a promising indicator of the prognosis of renal cell carcinoma." (PMID 38566133, 2024).
retinal degeneration (2 papers, 2022). Degeneration of the retina. "PGRMC1 expression has been demonstrated to be upregulated in the setting of retinal degeneration in the rd10 mouse retina." (PMID 36266625, 2022). "This study illustrated that EC, which may become a promising therapeutic strategy for AMD, prevented NaIO3-induced retinal degeneration, and this improvement may be associated with the mitochondrial quality control and the TMEM97/PGRMC1/Aβ signaling pathway." (PMID 35833100, 2022).
schizophrenia (2 papers, 2012 to 2017). A major psychotic disorder characterized by abnormalities in the perception or expression of reality. "Of the 8 known genes in this list, PGRMC1 was located in the Blue module, confirming over-expression in schizophrenia." (PMID 22761806, 2012).
thyroid tumor (2 papers, 2015 to 2021). A benign or malignant neoplasm affecting the thyroid gland. "PGRMC1 is essential for tumor formation, invasion and metastasis, and is upregulated in breast, colon, lung and thyroid tumors." (PMID 27867772, 2015). "Progesterone receptor membrane component 1 (PGRMC1) has been shown to impact drug resistance and cancer stemness in breast, colon, lung, and thyroid tumors." (PMID 34680249, 2021).
adenoma (1 paper, 2022). A neoplasm arising from the epithelium. "A novel marker, progesterone receptor membrane component 1 (PGRMC1) was studied in canine adenomas and carcinomas as well as in healthy canine mammary gland tissues." (PMID 36288138, 2022).
adenomyosis (1 paper, 2022). The growth of endometrial tissue inside the muscular wall of the uterine corpus. "The protein expression of PGR, mPRα, mPRβ, and PGRMC1 was significantly higher in adenomyosis compared to the normal myometrium (Figure A1a–c,e), while mPRγ and PGRMC2 had similar expression in both tissues (Figure A1d,f)." (PMID 35956024, 2022).
adrenal pheochromocytoma (1 paper, 2017). "mPRβ mRNA was drastically increased during NGF-induced neurogenesis in PC12, a rat adrenal pheochromocytoma cell line, whereas the expression of other progesterone receptors such as mPRα, Progesterone Receptor (PR), and PGRMC-1 did not exhibit the same expression profile." (PMID 28701790, 2017).
Alcohol Abuse and Alcoholism (1 paper, 2023). "In light of this evidence, to assess the role of Pgrmc1 in ALD we used the National Institute on Alcohol Abuse and Alcoholism (NIAAA) model (for chronic and binge alcohol feeding) for inducing ALD in whole body Pgrmc1 KO mice." (PMID 37070746, 2023).
Anorexia (1 paper, 2024). Lack of desire to eat (loss of appetite). "Our data indicate a hypomethylation of PGRMC1 in patients with anorexia; however, this pathway is not clearly known to be involved in this condition." (PMID 39519555, 2024).
anovulation (1 paper, 2010). The absence of ovulation. "The aim of this study was to determine the natural expression levels of PGRMC1 in an easy accessible tissue throughout the menstrual cycle and to assess PGRMC1 levels in conditions associated with reduced fertility and anovulation." (PMID 20537145, 2010).
autosomal recessive retinitis pigmentosa (1 paper, 2017). Autosomal recessive retinitis pigmentosa (RP) is an autosomally recessive inherited retinal dystrophy leading to progressive loss of the photoreceptors and retinal pigment epithelium and resulting in blindness usually after several decades. "Progesterone receptor membrane component 1 (PGRMC1) is a key regulator of apoptosis, and its up-regulation was found in retinal degeneration 10 (rd10) mice, which are a model system for autosomal recessive retinitis pigmentosa." (PMID 29137141, 2017).
bladder cancer (1 paper, 2017). "These included proteins previously associated with bladder cancer and also additional novel such as PGRMC1, FUCA1, BROX and PSMD12, which were further confirmed by immunohistochemistry." (PMID 29050215, 2017).